CD9 (CD9 molecule)
Diseases named in the same sentence as CD9 in open-access papers (continued):
Sharing a sentence is not in itself a finding about the gene and the disease.
lung carcinoma (25 papers, 2003 to 2025). "The subgroup analysis was also performed, which revealed that the associations between CD9 downregulated expression related to poor OS in lung cancer and head and neck cancer." (PMID 34868985, 2021). "In conclusion, our study shows that CD9-positive plasma exosomes are associated with both lung cancer and HIV, prior chemotherapy, as well as with survival, suggesting a possible prognostic value." (PMID 34680341, 2021). "Interestingly, low levels of CD9 expression have been previously implicated in the poor prognosis of lung cancer patients." (PMID 22629454, 2012). "Furthermore, EVs isolated with anti-CD61 beads enclosed mRNA expression patterns that might be associated to early-stage lung cancer, in contrast with EVs captured through CD9, CD63 or CD81." (PMID 35933395, 2022). "After intrathoracic implantation of lung cancer cells, metastasis to lymph nodes was diminished and accompanied by decreased neoangiogenesis and lymphangiogenesis in CD9 knock-out mice." (PMID 37007105, 2023). "The aim of our retrospective study was to assess the potential clinical value of CD9-positive plasma exosomes in lung cancer patients, patients with lung granulomas, healthy individuals, and HIV-positive patients with or without lung cancer." (PMID 34680341, 2021). "This study investigates the clinical significance of CD9-positive plasma exosomes in lung cancer patients, healthy individuals, and HIV-positive patients with or without lung cancer." (PMID 34680341, 2021). "This study shows that CD9-positive plasma exosome concentrations differ between healthy controls, patients with immunocompetent pulmonary granulomas and patients with lung cancer." (PMID 34680341, 2021). "Western blotting analysis of 10K and 100K pellets in lung cancer cell lines was based on CD9 and CD63 as markers of small EVs (exosomes), and BiP and Annexin A1 as markers of large EVs (oncosomes)." (PMID 32634139, 2020). "LC-MS/MS analysis in CD9 immunoprecipitates of crosslinker DTME-treated lung cancer cells identified direct interactions with claudin-1 although other claudins (claudin-2, −3, −4, −5, and −7) associated to a much lesser extent." (PMID 32091301, 2020). "By way of example, CD9 was the focus of a proof-of-principle study to assess the efficacy of a gene therapy approach to counter lung cancer metastasis." (PMID 30566430, 2018). "Adenoviral transduction of CD9 in an orthotopic lung cancer model was shown to significantly inhibit lymph node metastasis." (PMID 30566430, 2018). "Recent findings have identified CD9-positive exosome subpopulations as progressive markers for lung cancer in HIV-positive individuals, exhibiting notably lower concentrations in the plasma of HIV-positive lung cancer patients than in that of HIV-positive individuals without cancer." (PMID 38607736, 2024). "In addition, negative MRP-1/CD9 expression was associated with a poor prognosis in breast cancer, lung cancer and pancreatic cancer." (PMID 12838318, 2003). "In accordance with the Minimal Information for Studies of EVs 2024 (MISEV), several known EV markers, including CD9, CD81, Flotillin-1, and TSG101, were observed in the purified serum EVs of patients with lung cancer and healthy individuals." (PMID 41007624, 2025). "While CD4 is the primary receptor for IL-16, certain cells can respond to IL-16 through alternative receptors like CD9, for example, mastocytes or lung cancer cells, as well as via CD4- and CD9-independent mechanisms." (PMID 39408600, 2024). "This study applied SPR and QCM-D to studythe concentration of EVs using three well-defined tetraspanin biomarkers(CD9, CD63, and CD81) in lung cancer cells." (PMID 37307147, 2023). "CD9 and CD81 are KLF4 transcriptional targets, regulating KLF4-CD9/CD81-JNK signaling pathway and TGFβ1/SMAD signaling pathway, indicated some KLFs via different mechanisms play important roles in inhibiting the growth of lung cancer." (PMID 38560274, 2024).
lung carcinoma (continued). "By applying targeted mass spectrometry with stable isotope-labeled peptide standards, we assessed the levels of 28 EV-associated proteins, including the conventional exosome markers CD9, CD63, CD81, CD82, and HSPA8, in vesicles derived from the lung cancer cell lines NCI-H23 and A549." (PMID 34684727, 2021). "We noted that CD9, present in both the FSL and RSL, was increased in 41.2% of lung cancer cases." (PMID 23374247, 2013). "In addition, CD9-positive plasma exosomes are increased in HIV seropositive and HIV seronegative lung cancer patients compared to healthy controls, while chemotherapy-treated lung cancer patients have lower plasma exosome levels." (PMID 34680341, 2021). "In summary, we report for the first time that CD9-positive plasma exosomes are increased in HIV seropositive and HIV seronegative lung cancer patients compared to healthy controls, while chemotherapy-treated lung cancer patients have lower plasma exosome levels." (PMID 34680341, 2021). "However, seven genes selected from FSL (FOXA2, C4BPA, SCGB3A1, DDX58, CCNDBP, TMSB4X, and CXCL17), and one gene selected from both FSL as well as RSL (CD9), were up-regulated in the lung cancer tissues, but not significantly (P > 0.05)." (PMID 23374247, 2013).
pancreatic cancer (22 papers, 2003 to 2026). "Recently, Jérémy Nigri and colleagues showed that CD9 on the surface of EVs facilitates the uptake of EVs from cancer-associated fibroblasts by pancreatic cancer cells." (PMID 36941633, 2023). "It has been reported that CD9 identifies a subpopulation of pancreatic cancer stem cells (CSCs) able to initiate and sustain pancreatic cancer growth as demonstrated in CD9 deficient organoid and mice models." (PMID 37007105, 2023). "CD9 on sEVs derived from CAFs plays a crucial role in the uptake of sEVs into pancreatic cancer cells and contributes significantly to pancreatic cancer progression." (PMID 39684264, 2024). "Mechanistically, CD9 enhances glutamine uptake in pancreatic cancer cells via promoting the plasma membrane localization of the glutamine transporter ASCT2." (PMID 36941633, 2023). "Antibody targeting of CD9 in pancreatic cancer disrupted CD9/ADAM interactions and led to decreased proliferation, migration and colony formation." (PMID 37007105, 2023). "Higher positive expression of CD9 has served as a good prognostic marker in breast, lung, colon, and pancreatic carcinomas, as it is thought to have a metastatic suppressor role by inhibiting tumor cell motility, at least in vitro." (PMID 34065085, 2021). "In our studies, the proportion of CFSE+ EVs and of CD9+ events within CFSE+ EVs increased in the plasma of mice bearing liver metastatic pancreatic cancer lesions." (PMID 33195266, 2020). "In contrast, the expression of exosome-related proteins, such as RAB27A, TSG101 and CD9, increased immediately after radiation in pancreatic cancer cells." (PMID 32228703, 2020). "CD9 was also identified as a marker of pancreatic cancer-initiating cells." (PMID 36941633, 2023). "Low CD9 expression is related to poor prognosis in several cancers including pancreatic cancer." (PMID 24708694, 2014). "Researchers have reported that an increased CD9 expression is a favorable survival factor in patients with bladder, breast, colorectal, esophageal, head and neck, gallbladder, lung, and pancreatic cancer, as well as malignant mesothelioma, acute myeloid leukemia, and follicular lymphoma." (PMID 34493282, 2021). "Similar to the characterisation of EVs from human pancreatic cancer cell lines, Alix, TSG101 and CD9 were detected whereas calreticulin and GAPDH were undetected in the P100 fractions from KPC and TPAC cells after ultracentrifugation." (PMID 39863771, 2025). "In contrast, the downregulation of CD9 promoted cancer growth and metastasis through the upregulation of EGF in pancreatic cancer." (PMID 37007105, 2023). "Conventional vesicles have high concentrations of tetraspanin proteins such as CD63, CD9, and CD81, in addition to Hsp70, which is a pancreatic cancer-specific marker that has also been reported in the exosomal or extravesicular population." (PMID 36002889, 2022). "sEVs labeled TSPAN8 and other tetraspanins (e.g., CD9 and CD63) are highly expressed in pancreatic cancer cells." (PMID 34980146, 2022). "Through our ELISA assay we measured levels of different exosome populations, in particular those carrying the ubiquitous CD9, CD81 and some markers already found in tumour exosomes of pancreatic cancer such as CD44v6, Tspan8, EpCAM, CD24, CXCR4, Integrins α6 and β4, CD133." (PMID 31048929, 2019). "Five proteins including CD9, perlecan (HSPG2), apolipoprotein E (APOE), stromal cell derived factor 4 (SDF4), and fibronectin receptor/integrin β1 (ITGB1) were subsequently validated by immunohistochemistry on human pancreatic cancer tissue." (PMID 24708694, 2014). "Furthermore, CD9 could directly bind to ADAM10, ADAM9 and ADAM17 in pancreatic cancer cells." (PMID 38389703, 2024).
COVID-19 (17 papers, 2021 to 2024). A disease caused by infection with severe acute respiratory syndrome coronavirus 2. "To characterize the protein cargo associated with EVs in COVID-19 patients, we employed three distinct EV isolation methods: CD9+ affinity immunocapture, mS1 EV-ganglioside capture, and size-exclusion chromatography." (PMID 39569406, 2024). "Our analyses also suggest a differential miRNA expression between CD63+/CD81+/CD9+ serum small‐EVs from mildly and severely ill Covid‐19 hospitalized patients, which will require further evaluation." (PMID 34122779, 2021). "Strikingly, in our analysis of non-COVID-19 health care workers (G3) we found that after 8 months post-sample collection there were statistically significant changes in the abundance of 194 proteins associated to CD9+-EVs when compared to the primary time point (124 up and 70 downregulated)." (PMID 39569406, 2024). "Our findings were remarkable, especially considering a report that detected the Spike protein using different technologies including Western-blot analysis after enriching CD9/CD81/CD63 EV subpopulations in COVID-19 patients." (PMID 39569406, 2024). "In particular, CD9 molecules play a key role in loading exosomal cargo by the protein–protein interaction network, supporting a pivotal role in loading COVID-19 virus proteins, as well as participating in exosome biogenesis." (PMID 33925492, 2021). "The total number of EVs markers was also found significantly increased in severely affected patients when compared to both mild/asymptomatic patients and non-infected subjects, suggesting an increased amount of circulating CD9+-EVs in severe COVID-19 individuals." (PMID 39569406, 2024). "Interestingly, our differential expression analysis of CD9+EVs cargo from severe COVID-19 patients and non-COVID-19 individuals showed two distinctive signatures of anti-viral response." (PMID 39569406, 2024). "Circulating CD9+-EVs from COVID-19 patients were initially isolated by a two-step purification procedure involving 120,000 xg ultracentrifugation of plasma samples that generate p120 fractions followed by CD9+-EVs magnetic immunocapture." (PMID 39569406, 2024). "The total number of proteins identified in CD9+-EVs showed a slight decrease in severe COVID-19 patients at the convalescent stage and remained unchanged in mild/asymptomatic COVID-19 and control group." (PMID 39569406, 2024). "Volcano plots illustrating statistical comparison of the abundance of human proteins detected in CD9+-EVs from severe COVID-19 patients and non-COVID-19 individuals showed 140 proteins differentially upregulated in infected patients with severe symptoms (q val= 0.05)." (PMID 39569406, 2024). "Notably, overexpression of the CD9 and CD63 shows the involvement of extracellular vesicles in COVID-19 pathogenesis and can be associated with the faster virus spreading, mediating communication between infected and virus free cells." (PMID 36230912, 2022). "EVs collected from the serum of both healthy controls and patients with COVID-19 were confirmed by transmission electron microscopy, and western blotting confirmed the expression of CD9, CD63, and flotillin-1, while calnexin and haptoglobin expressions were negative." (PMID 36451245, 2022). "Both CD9 and CD63 are involved in exosome formation, and COVID-19 plasma exosomes stimulate pro-inflammatory responses that affect CD4/CD8 T cells, and CD14+ monocytes." (PMID 39712003, 2024). "Considering the overall median fluorescence intensity (MFI) for specific EV markers (i.e., tetraspanins CD63, CD9 and CD81) we observed that only EV-specific tetraspanin CD81 was significantly higher in COVID-19 patients than controls (P<0.05)." (PMID 37207201, 2023). "In this study, we found several exosomes including CD9, CD31, CD40, CD45, CD41b, CD42a, CD62P, CD69, CD81, CD105, and HLA-DRDPDQ in the plasma of COVID-19-recovered pregnant women were significantly less abundant than the control group." (PMID 35647028, 2022).
COVID-19 (continued). "Tetraspanin monoclonal antibodies (anti-CD9, anti-CD63 and anti-CD81) have been demonstrated to inhibit the COVID-19 entry stage." (PMID 36101528, 2022). "When comparing MILD and SEVERE COVID-19 patient-recovered exosomes, we found that SARS-CoV-2-S peptides were drastically more enriched in the CD41a+ and CD9+ subpopulations of those recovered from MILD patients." (PMID 35111156, 2021). "By label-free detection, we observed that most of the exosomes were captured by anti-CD9 and anti-CD41a antibodies, and intriguingly, exosomes of MILD COVID-19 patients were remarkably more abundant compared to those of both SEVERE patients and HDs." (PMID 35111156, 2021). "By visualizing and quantifying the levels of SARS-CoV-2-S fragments on bead-purified CD9+ exosomes, we confirmed a significant enrichment of SARS-COV-2-S peptides in MILD COVID-19 patient compared to SEVERE COVID-19 patient exosomes." (PMID 35111156, 2021). "Common uEV biomarkers including annexin A2, HSP70, and CD9 were all present in each uEV preparation from the COVID-19-negative and COVID-19-positive participant groups, and the levels of each biomarker were generally comparable between the two groups." (PMID 39861814, 2024). "This agrees with the absence of changes also observed in CD9+-EVs content of this group at m0 when compared to non-COVID-19 individuals, confirming that circulating CD9+-EVs are not altered by mild/asymptomatic SARS-CoV-2 infection." (PMID 39569406, 2024). "We did not identify viral proteins in COVID-19 plasma exosomes that were positive for the exosome marker CD9, although exosomes from culture supernatants of A549 cells overexpressing S and N proteins contained both S and N proteins." (PMID 36526691, 2022). "Because ACE2 is present in tetraspanin-enriched microdomains, where it clusters with other glycoproteins, such as CD9, CD81, and TMPRSS2, we also established assays to define whether anti-IgM antibodies against any of these proteins were present in COVID-19 sera." (PMID 35349483, 2022). "We found that molecules involved in platelet degranulation (CD9, platelet factor 4 (PF4)), aggregation, and activation [CD9, CLEC1B (also known as CLEC2)] were upregulated dramatically in COVID-19 EVs, while none of these proteins were detectable in EVs from healthy donors." (PMID 35820906, 2022).
liver fibrosis (16 papers, 2019 to 2025). "In liver cirrhosis, the scar-associated macrophages, which were defined as TREM2+CD9+ macrophages, differentiated from circulating monocytes and expanded in liver fibrosis." (PMID 37380987, 2023). "Macrophage, populated in the liver during NAFLD, express a high level of Spp1, Cd9, and Trem2 and participate in hepatic fibrosis." (PMID 37822923, 2023). "It is worth noting that this subpopulation is also classified as pro-fibrotic, as TREM2+CD9+ macrophages expand in liver fibrosis." (PMID 36982747, 2023). "A study in 2019 identified a subpopulation of profibrotic TREM2+CD9+ macrophages, which had a key role in the progression of liver fibrosis." (PMID 36503486, 2022). "In line with this concept, OPN a major protein we found secreted by CD9+ senescent macrophages in obese state has been shown to delay resolution of liver fibrosis." (PMID 35181634, 2022). "The median fibulin‐4/CD9 ratio was found to increase as liver fibrosis progressed." (PMID 38853023, 2024). "We also found that T3 could inhibit the profibrotic TREM2+CD9+ macrophage, which had been identified an important player in the progression of liver fibrosis." (PMID 36503486, 2022). "In our study, we found that T3 could inhibit the profibrotic macrophage TREM2+CD9+ macrophage, which had been identified an important player in the progression of liver fibrosis." (PMID 36503486, 2022). "The results of this study showed a significant correlation between this profibrotic macrophage subset (CD9+TREM2+ macrophages) and the severity of liver fibrosis in patients with NAFLD." (PMID 37415134, 2023). "Application of scRNA-seq method, TREM2+CD9+ macrophages and ACKR1+PLVAP+ endothelial cells were identified and expanded in liver fibrosis." (PMID 35791909, 2022). "Along with the progression of liver fibrosis, IGHV, GAPDH, C1s, GRP78 and V-ATPase levels significantly increased, and PPBP, CD9, Lp(a) and SAP levels significantly decreased." (PMID 35797333, 2022).